SLFN11 (schlafen family member 11)
Diseases named in the same sentence as SLFN11 in open-access papers (continued):
Sharing a sentence is not in itself a finding about the gene and the disease.
cancer (continued). "As the authors concluded, the results suggest that SLFN11 levels in both cancer and non-cancer cells may play a role in response to platinum-containing regimens in HGSC." (PMID 35625957, 2022). "While SLFN11 is an established marker for sensitivity to DDA-mediated cancer cell killing, its role as a repressor of NFκB2 mediated transcription may complicate targeted approaches aiming to activate SLFN11 in GBM." (PMID 36382088, 2022). "Hence, stimulation of SLFN11 expression via promoter demethylation by histone deacetylase inhibitors has been suggested as a strategy to sensitize cancer cells to DDA." (PMID 36382088, 2022). "The study suggested that SLFN11 may induce apoptosis and enhance the sensitivity of cancer cells to PARP inhibitors by enhancing S-phase arrest." (PMID 35715750, 2022). "SLFN11 enhances cancer cell sensitivity to DNA-damaging agents, through a peculiar mechanism." (PMID 36110934, 2022). "Based on detailed analyses of cancer cell lines, neither clinically meaningful SLFN11 mutations nor its copy number variations have been reported." (PMID 35625957, 2022). "In this study, we aimed to gain insights into the role of SLFN11 as a biomarker in cancer." (PMID 33339894, 2021). "Interestingly, we found varied SLFN11 transcript and protein levels in the different cancer types and noted some concordance between transcript levels in cell lines and protein levels in PDX models." (PMID 33339894, 2021). "Our next goal was to determine SLFN11 transcript and protein levels in different cancer models." (PMID 33339894, 2021). "Here, we implemented a pipeline to quantify SLFN11 in human cancer samples." (PMID 34549724, 2021). "To explore this hypothesis, we performed principal component analysis (PCA), including cancer cellularity together with immune cell subpopulations correlating with SLFN11 with FDR < 0.05." (PMID 34549724, 2021). "However, only in a small amount of studies, this low expression of SLFN11 in primary cancers as well as in commonly used cancer cell lines has been associated with epigenetic silencing, and mainly, DNA hypermethylation of the promoter." (PMID 33668490, 2021). "As for its role in DNA damage response, independent studies have shown that SLFN11 augments the sensitivity of cancer cells to a wide range of DNA-damaging agents including platinum-derivatives, topoisomerase inhibitors, PARP inhibitors and replication inhibitors." (PMID 33513156, 2021). "We next sought to evaluate SLFN11 H-scores selectively in the cells from cancer tissue." (PMID 34549724, 2021). "Here, we review cancer-associated replication stress (RepStress) and its genomic signature, and propose how to utilize RepStress-targeted therapies in the context of ATR inhibitors and Schlafen 11 (SLFN11)." (PMID 34572827, 2021). "In addition to AraC, the activity of camptothecin (CPT), a topoisomerase inhibitor was also found correlated to SLFN11 expression in 31 B-cell-derived cancer cell lines available in the GDSC database." (PMID 33513156, 2021). "IHC assessment may therefore need to specify whether the SLFN11-positive cells are cancer cells and/or stromal cells." (PMID 34572827, 2021). "Moreover, we provided mechanistic insights into the link between SLFN11 cancer immunity and DNA-damaging treatment." (PMID 34549724, 2021). "In summary, in all the analysed cancer models, SLFN11 status was linked to outcomes from DDA treatments and the resistant SLFN11 low population could be re-sensitised to DDA by combinations with ATR, WEE1 or CHK inhibitors." (PMID 33339894, 2021). "SLFN11 inactivation in cancer cells is primarily driven by epigenetic modifications." (PMID 34572827, 2021). "In serial sections of HGSOC tissues, we could observe high SLFN11 protein in those immune cell subtypes, particularly in monocytes/macrophages (for representative HGSOCs with varied SLFN11 protein in cancer cells)." (PMID 34549724, 2021).
cancer (continued). "SLFN11 protein was assessed with our IHC assay in 472 PDX models from different cancer types." (PMID 33339894, 2021). "Taken together, the available literature suggests that SLFN11 may play a so far incompletely understood role in an intertwined process of cancer and immune response to DDA-based chemotherapies." (PMID 34549724, 2021). "SLFN11, one of the 5 human SLFNs, is a putative DNA/RNA helicase concentrated in the nucleus and has a dominant role in sensitizing malignant cells to DNA-targeting anti-cancer agents." (PMID 33218331, 2020). "Prior studies that evaluated SLFN11 as a prognostic or predictive biomarker in cancer patients." (PMID 31682620, 2019). "In addition, high levels of SLFN11 confer sensitivity of cancer cell lines to topoisomerase inhibitors, alkylating agents and DNA synthesis inhibitors, including gemcitabine." (PMID 29152060, 2017). "The DNA methylation microarray approach in the NCI60 panel of cancer cell lines revealed SLFN11 methylation (higher than 0.5) in 25% (15 of 59) of cell lines, whereas for the remaining 75% (44 of 59) of cell lines the 5′-end CpG island remained unmethylated (lower than 0.5)." (PMID 26625211, 2016). "Future research directions based on SLFN11 should focus on the selection of evaluation methods, dynamic monitoring technology, optimization of combination therapy, elucidation of molecular mechanisms, cross-cancer validation, and regulation of the immune microenvironment." (PMID 40766331, 2025). "Therefore, the increase in SLFN11 levels observed during platinum-based therapy may be due to the activation of the DNA damage response pathways, replication stress in cancer cells, and the cells’ attempt to repair the chemotherapy-induced DNA damage." (PMID 38790938, 2024). "Given that phase 1 clinical trials with TAK-243 are underway in patients with advanced solid tumors and blood cancers (NCT02045095 and NCT03816319), our results imply that the expression status of SLFN11 might be utilized to predict therapeutic benefit of TAK-243 in cancer treatment." (PMID 35903760, 2022). "Hence, in some cancers SLFN11 may execute additional roles, besides its DDA sensitizing ability, that may contribute to tumor progression." (PMID 36382088, 2022). "A better understanding of Schlafen proteins could open up new avenues in cancer management, for instance, diagnostics that monitor activity levels of one such protein, SLFN11, could help oncologists predict how well patients might respond to anti-cancer therapies." (PMID 35768579, 2022). "Of interest, a moderate association between cancer and noncancer SLFN11 levels could be observed (ρ = 0.50, FDR = 0.0208)." (PMID 34549724, 2021). "Validation of SLFN11 in a clinical setting (either in AS or in other, more common cancers in which patient inclusion is less challenging) may enable the design of a biomarker-driven basket study to investigate PARPi and TMZ combination therapy in cancer patients with SLFN11-positive tumors." (PMID 34085099, 2021). "We also aimed to gain mechanistic insights into the link between SLFN11 cancer immunity and DNA-damaging treatment, and most importantly, we investigated whether SLFN11 could represent a relevant prognostic biomarker to platinum-based treatment response in patients with advanced-stage HGSOC." (PMID 34549724, 2021). "Likewise, SLFN11 low pan-cancer cell lines globally benefitted from the combination of SN-38 with different inhibitors of the CHK kinase (SRA737, which targets preferentially CHK1, or prexasertib (a double CHK1/2i) (respectively) or WEE1i (right), but not by combination with olaparib (right)." (PMID 33339894, 2021). "Apart from its antiviral properties, recent studies have indicated that SLFN11 could enhance the sensitivity of cancer cells to DNA-damaging agents (DDAs) and may be a potential robust biomarker to predict response to DDAs in ovarian, lung, and colorectal cancers 11-13." (PMID 32292519, 2020).
cancer (continued). "Furthermore, these data suggest that SLFN11 expression could be used as a biomarker to identify Ewing sarcoma tumors with sensitivity to eltrombopag, as well as identify other cancer types that could benefit from eltrombopag treatment." (PMID 33256675, 2020). "However, given that these cancers develop chemotherapy resistance within a few months after initial treatment, we predicted that SLFN11—a biomarker of cisplatin and PARP inhibitor response—may be downregulated following platinum-based chemotherapy." (PMID 28212573, 2017). "Overall, this suggests that the ETS transcription factors regulating SLFN11 may be cancer-specific." (PMID 28212573, 2017). "However, little is known about SLFN11 functions in cancer cells." (PMID 27901484, 2017). "Our findings suggest that high SLFN11 and low ATM expression levels predict PARP inhibitor response in PDX models and/or cell lines, whereas standard biomarkers of PARP inhibition defined in other cancer types (mutational burden, Myriad HRD score, and mutations in DDR genes) do not." (PMID 28212573, 2017). "This conclusion could have broad implications as 45-50% of cancer cell lines inactivate SLFN11." (PMID 27708213, 2016). "Notably, the predictive value of SLFN11 may extend to other cancers." (PMID 40766331, 2025). "Schlafen family member 11 (SLFN11) DNA/RNA helicase has been identified as a biomarker that when upregulated in SCLC, correlates with increased cancer destruction when PARP inhibitor therapy is introduced." (PMID 40507328, 2025). "SLFN11 expression suppressed CRC growth in vitro and in vivo and sensitized cancer cells to cisplatin." (PMID 40105034, 2025). "We identify SLFN11, ETV4, HNRNPA1, and CMTM7 as promising markers of drug sensitivity in a number of common cancers." (PMID 39494610, 2024). "SLFN11 represents another member of subgroup III of SLFNs and has widely been considered a predictive biomarker for cancer cell chemosensitivity to various DDAs." (PMID 38791884, 2024). "SLFN11, SLFN5, SLFN13, and SLFN12 are broadly transcribed in cancer cells, while SLFN12L, SLFN14, and SLFNL1 display reduced levels of expression." (PMID 39558948, 2024). "Some preclinical studies using CRISPR/Cas9 technology have highlighted the importance of some genes, including SLFN11, APE1, RSF1, and CDK5, in cancer drug resistance." (PMID 35715750, 2022). "SLFN11, SLFN5, SLFN13, and SLFN12 exhibit a wide range of transcription levels in cancer cells, whereas SLFN12L, SLFN14 and SLFNL1 are barely expressed in cancer cell lines." (PMID 35768579, 2022). "Remarkably, SLFN11 expression is bimodal in cancer cell lines with ~50% of the NCI, CCLE and GDSC cancer cell lines expressing high SLFN11 and the other ~50% cell lines not expressing SLFN11." (PMID 34572827, 2021). "SLFN11 expression is also strongly correlated with the expression of CD47, a cell surface marker that sensitizes cancer cells to chemotherapy and radiotherapy, in RCC, while exogenous SLFN11 overexpression sensitizes CD47 negative cancer cells to radiotherapy." (PMID 34571887, 2021). "Furthermore, SLFN11 was not correlated with ploidy or mutational burden in cancer." (PMID 33339894, 2021). "SLFN11 expression was found to be correlated to PARP inhibitor response, especially talazoparib, in the NCI-60 panel of human cancer cell lines and was experimentally shown to sensitize cancer cells to PARP inhibitors including olaparib." (PMID 33803939, 2021). "While SLFN11 overexpression is used as a biomarker of PARP inhibitor sensitivity, SLFN11 is inactivated in 50% of cancers and frequently silenced due to promoter methylation." (PMID 32029455, 2020). "A better understanding of the mechanisms that allow SLFN11-mediated toxicity following IFN-γ exposure should be of value to enhance the anti-tumor effect of T and NK cell-based cancer immunotherapies." (PMID 30753225, 2019).
cancer (continued). "Schlafen family member 11 (SLFN11), with the highest degree of 19, was recently discovered as a dominant response factor of cancer cells to topoisomerase I inhibitors." (PMID 29423044, 2018). "SLFN11 levels directly confer chemotherapy and/or PARP inhibitor sensitivity in a number of cancer types, but it is unclear how this is controlled." (PMID 28212573, 2017). "By contrast, cancer cell lines unmethylated at the SLFN11 promoter (U251, NCI-H23, DU145 and SK-OV-3) expressed highly detectable SLFN11 RNA transcript and protein levels." (PMID 26625211, 2016). "First, pan-cancer prospective clinical trials should evaluate the predictive power of SLFN11-guided therapies, especially in patients without BRCA mutations or homologous recombination deficiency." (PMID 40766331, 2025). "For tumors with low SLFN11 expression, systematically evaluate the efficacy of the combination regimens of ATR inhibitors, ATM inhibitors, CHK1 inhibitors, and WEE1 inhibitors with standard chemotherapy in different cancers." (PMID 40766331, 2025). "Pan-cancer drug sensitivity profiles suggest that the role of SLFN11 is not lineage specific and instead exerts effects that are common to multiple different biological contexts." (PMID 41372167, 2025). "Yet, evidence now shows that epigenetic silencing via DNA methylation, deacetylation, and post-translational phosphorylation can downregulate key members like SLFN11 and SLFN12, driving chemoresistance and poor outcomes in cancers such as gastric, colorectal, and ovarian tumors." (PMID 41303540, 2025). "SLFN11 has been highlighted as a potential marker for cancer cell chemosensitivity in platinum-based drugs, topoisomerase inhibitors, poly-ADP ribose inhibitors, and antibody-drug conjugates in over ten cancer types." (PMID 39594803, 2024). "SLFN11 was not induced following treatment with IFNα in activated T cells and this is similar to observations from cancer cells where IFNα induced expression of most SLFNs but not SLFN11, suggesting an altered activation pathway for SLFN11." (PMID 38791884, 2024). "Relevant alterations range from genetic aberrations (e.g. AR-gain or mutations) to transcriptional changes such as alternative splicing (e.g. AR-V7), expression of PSMA and SLFN11, or upregulation of neuroendocrine markers (e.g. SYP, CHGA, NCAM1, and DLL3) in cancers cells." (PMID 39550585, 2024). "A lack of SLFN11 expression renders a variety of cancers resistant to certain DDAs, as was demonstrated for topoisomerase I and II inhibitors, alkylating agents, and DNA synthesis inhibitors (e.g., gemcitabine)." (PMID 38791884, 2024). "Lack of Schlafen family member 11 (SLFN11) expression has been recently identified as a dominant genomic determinant of response to DNA damaging agents in numerous cancer types." (PMID 38001424, 2023). "Since SLFN11 expression has been shown to be inducible by IFN, and regulated by methylation, we explored both mechanisms to increase endogenous SLFN11 expression in cancer cell lines." (PMID 38001424, 2023). "According to the findings from preclinical studies, approximately 50% of cancer cell lines do not express SLFN11, making its expression bimodal." (PMID 35625957, 2022). "A detailed immunohistochemistry and RNA expression study recently showed that SLFN11 is expressed in normal human brain and immune cells, not only cancer cells." (PMID 35903760, 2022). "Unlike the 100% SLFN11 positivity in non-tumor tissue, a total of 14 cancer samples (38%) were evaluated as SLFN11-negative." (PMID 35625957, 2022). "Confidence in the automated digital pathology allowed us to launch an automated assessment of SLFN11 levels in either cancer or noncancer cells in each slide from the FFPE tissue samples." (PMID 34549724, 2021).
cancer (continued). "Epigenetic modifications, which are frequent in tumorigenesis and chemoresistance, are responsible for the lack of SLFN11 expression in many cancer cells, resulting in chemoresistance to widely used clinical agents that target DNA replication." (PMID 34572827, 2021). "CD47 mRNA expression is positively correlated with SLFN11 mRNA expression in a subset of human cancers but not in the corresponding nonmalignant tissues in TCGA." (PMID 33925464, 2021). "Cancer cellularity showed a negative correlation with SLFN11 expression in TCGA HGSOC set (ρ = –0.30, FDR < 0.0001)." (PMID 34549724, 2021). "As our results indicated, SLFN11 was associated with the response to platinum-based treatment in HGSOC, due to its expression in both cancer and noncancer (immune-related) cells." (PMID 34549724, 2021). "Although SLFN11 knockdown does not protect CD47-null PC3 cells from the effect of ionizing radiation as in other cancer cells, the low SLFN11 in CD47-null PC3 cells reduces the sensitivity of these cells to DNA damaging agents such as etoposide." (PMID 34571887, 2021). "SLFN11 informs on the standard of care chemotherapy based on DDA and the effect of selected combinations with ATR, WEE1 or CHK1 inhibitor in a wide range of cancer types and models." (PMID 33339894, 2021). "First, we evaluated the impact of SLFN11 overall H-score, H-score in cancer and noncancer cells, stage, age, and TIL infiltration on PFI by univariable statistics." (PMID 34549724, 2021). "In turn, these findings would explain why overall SLFN11 H-score is a stronger prognostic biomarker than either cancer or noncancer SLFN11 measured separately." (PMID 34549724, 2021). "Considering the significant role of the mTOR signaling pathway in many types of cancer 38-40, mTOR inhibitors may be effective in HCC patients with low SLFN11 expression." (PMID 32292519, 2020). "In all the cancer types where adequate methylation data was available, SLFN11 mRNA expression was negative correlated with SLFN11 promoter methylation." (PMID 31632920, 2019). "One mechanism of PARP inhibitor resistance that has been described for other cancer types is the downregulation of PARP1 itself, which we hypothesized directly affects SLFN11 levels." (PMID 28212573, 2017). "Because approximately 45% of cancer cell lines are SLFN11-negative at the transcript level, frequently by promoter hypermethylation, SLFN11 can be considered a testable biomarker to predict responders to PARPIs in addition to BRCA mutations and HRD." (PMID 27708213, 2016). "Conversely, upon efficient recovery of SLFN11 expression by transfection of the full-length SLFN11 protein in the hypermethylated and silenced HCT-15 and MCF7 cancer cell lines, we observed a significant increase in the sensitivity to cisplatin and carboplatin." (PMID 26625211, 2016). "The cancer cell lines HCT-116, HCT-15, MDA-MB-231, and MCF7, hypermethylated at the SLFN11 CpG island, had minimal expression of the SLFN11 RNA transcript, as determined by quantitative reverse transcription-PCR, and protein, as assessed by western blot and immunofluorescence." (PMID 26625211, 2016). "Thus, it is reasonable to speculate that SLFN11 epigenetic silencing compromises the correct partnership of DHX9 and BRCA1, and then it alters the correct function of the DNA damage response system, causing a shift in the platinum-associated chemosensitivity of the affected cancer cells." (PMID 26625211, 2016). "SLFN11 tends to not express in poor differentiation cancers and our results imply that it can sensitize CRC cells to respond to oxaliplatin-based treatment." (PMID 26525741, 2015). "This review consolidates compelling evidence demonstrating that SLFN11 expression strongly correlates with increased sensitivity to a wide array of DNA-damaging agents (DDAs), including platinum compounds, topoisomerase inhibitors, and PARP inhibitors across diverse cancer types." (PMID 40766331, 2025).